IL6 (interleukin 6)
Diseases named in the same sentence as IL6 in open-access papers (continued):
Sharing a sentence is not in itself a finding about the gene and the disease.
Insulin resistance (continued). "The potential mechanisms underlying VAI and FPG might include the following aspects: Excessive visceral fat promoted the secretion of increased inflammatory adipokine, including IL-6 and leptin, which might contribute to the occurrence of insulin resistance and diabetes." (PMID 36774500, 2023). "Similarly, IL-6 also has an important role in insulin resistance." (PMID 37513920, 2023). "Various studies determined that IL-6 and TNFα could promote insulin resistance." (PMID 37013538, 2023). "Insulin resistance and abdominal obesity are increasingly viewed as chronic inflammatory conditions, leading to the production of a wide variety of pro-inflammatory cytokines and chemokines, including IL-6, monocyte chemoattractant protein-1, TNF-α and other inflammatory factors." (PMID 37228109, 2023). "Both TNFα and IL-6 have been extensively studied and reviewed as promoters of an inflammatory response, with local recruitment of immune cells, such as macrophages, which contribute to chronic inflammation, and may in turn lead to insulin resistance in AT." (PMID 35557517, 2022). "Moreover, pro-inflammatory cytokine IL-6, a proven predictor of insulin resistance and T2D development, could induce NET production." (PMID 36247456, 2022). "Contrary to this information, it has been reported that IL-6, a pleiotropic cytokine, does not cause insulin resistance and may even be beneficial for diabetes in some cases." (PMID 34174798, 2022). "The possible mechanism of the relationship between VAI and insulin resistance is as follows:Visceral adipocytes secrete adipose-specific cytokines, such as leptin and adiponectin, as well as inflammatory cytokines (tumor necrosis factor-α and interleukin 6), which increase IR." (PMID 35937809, 2022). "In addition, P. gingivalis LPS is possibly implicated in insulin resistance, either by stimulating the activation of pro-inflammatory cytokines such as TNF-α and IL-6, which play important roles in insulin resistance, or by directly inhibiting glucose incorporation into smooth muscle cells." (PMID 35308549, 2022). "The hypertrophic adipocytes secrete pro-inflammatory cytokines such as tumor necrosis factor-α (TNF-α), interleukin 6 (IL-6), interleukin 8 (IL-8), and monocyte chemoattractant protein 1 (MCP-1) which, through the phosphorylation of insulin receptor substrate-1 (IRS-1), cause insulin resistance." (PMID 35406070, 2022). "In vivo studies showed that IL-10 could prevent IL-6 or lipid-induced insulin resistance." (PMID 35154341, 2022). "Indeed, acute IL-6 infusion is sufficient to induce insulin resistance in mice." (PMID 35474339, 2022). "Furthermore, the hypoxic conditions prevailing in early pregnancy stages induce the placental release of proinflammatory factors such as tumor necrosis factor alpha (TNF-α) and interleukin-6 (IL6), which are associated with insulin resistance and endothelial dysfunction." (PMID 35252239, 2022). "Pro-inflammatory cytokines such as CRP, interleukin-6 (IL-6) and tumour necrosis factor alpha (TNF-α) are derived from immune cells or adipocytes and are implicated in inhibiting the insulin signalling cascade whilst also positively associated with insulin resistance." (PMID 36145067, 2022). "Although an early study suggested the blockade of interleukin 6 signalings could ameliorate hepatic steatosis via modulating insulin resistance, it should be noted that this experiment was performed on mice instead of on human beings and the higher IL-6 level was caused by a high-fat diet." (PMID 35747747, 2022). "In addition, JNK knockdown mice have a decreased expression of pro-inflammatory cytokines such as TNF-α or IL-6, which might protect against insulin resistance in T2DM." (PMID 35455066, 2022). "However, the effect modifier role of IL-6 does not imply a causality role for IL-6 in insulin resistance in NMOSD patients." (PMID 33879088, 2021).
Insulin resistance (continued). "GAL-3BP is significantly positively associated with inflammatory markers, including IL6, IL-1β, together with TNFα, and these may participate in MetS pathogenesis related to GAL-3BP, since inflammation may probably result in insulin resistance." (PMID 34858323, 2021). "Moreover, inflammatory markers (interleukin 6, interleukin 1β, and tumor necrosis factor α), insulin sensitivity (fasting glucose, insulin, and homeostatic model assessment for insulin resistance index), and lipid profile (cholesterol, HDL, and LDL) significantly improved after TRE compared with ND." (PMID 34649266, 2021). "Overproduction of pro-inflammatory cytokines (including TNF- and IL-6) in adipose tissue, as well as an imbalance between adipokines that increase or reduce tissue sensitivity to insulin (adiponectin and resistin), are typical of insulin resistance disturbances." (PMID 34299201, 2021). "Moreover, insulin resistance is known to be associated with increased levels of proinflammatory cytokines such as C-reactive protein, tumour necrosis factor- (TNF-) α, interleukin- (IL) 1, and IL-6." (PMID 33597002, 2021). "In addition, increased levels of pro-inflammatory cytokines such as TNF-a, IL-8 and IL-6 have been reported in pregnancy complicated by GDM, suggesting that proinflammatory cytokines could be involved in the development of insulin resistance associated to GDM." (PMID 33477354, 2021). "Also, chronically elevated levels of inflammatory cytokines such as CRP, TNF-a, IL-6, and IL-1b could enhance insulin resistance (IR), disrupt insulin sensitivity, and consequently impair glucose homeostasis resulting in an increase in the risk of T2DM." (PMID 34917685, 2021). "In mice models with systemic inflammation and insulin resistance, there is accumulation of IL-6/IL-17 co-expressing T cells in the adipose tissue; these cells enhance leptin production, which eventually acts in synergy with IL-6 and IL-17 to promote Th17 differentiation." (PMID 34631754, 2021). "In contrast, IL-6-deficient mice (IL-6−/−) showed that absence of IL-6 leads to the development of inflammation and insulin resistance in the liver, indicating that IL-6 might also play beneficial roles in the improvement of insulin sensitivity." (PMID 32655424, 2020). "Therefore, the role of IL-6 in the development of insulin resistance remains controversial, and might be tissue and activation phase dependent." (PMID 32655424, 2020). "However, the role of IL-6 in insulin resistance seems to be more complex." (PMID 32655424, 2020). "Therefore, we treated adipocytes with TNF-α, which dramatically increased the expression of genes involved in insulin resistance in adipocytes, such as IL-6, CCL2, and chemokine ligand 9 (CCL9), but significantly reduced glucose transporter 4 (GLUT4) expression." (PMID 32024237, 2020). "In addition, decreased insulin resistance can lead to lower levels of proinflammatory cytokines, including tumor necrosis factor-alpha, interleukin-6, leptin, and chronic hepatic inflammatory markers, which have been associated with liver diseases including liver cancer." (PMID 33271947, 2020). "It has been reported that IL6 could induce hepatic insulin resistance." (PMID 32876525, 2020). "In contrast to adipocyte-specific IL6-deficient mice, the deletion of IL6 in both myeloid cells and muscle cells suppresses adipose tissue macrophage infiltration and either improves or at least minimally does not negatively affect insulin resistance." (PMID 32408016, 2020). "Studies have provided preclinical proof of concept that induction of bergamot may improve the phenotypical and morphological features of NASH along with reduction in adipose tissue inflammation and inflammatory cytokines, IL-6 and TNFα, hypoadiponectinemia, insulin resistance and dyslipidemia." (PMID 32903449, 2020).
Insulin resistance (continued). "Although it is not fully understood whether inflammatory cytokines are a cause of insulin resistance or are purely markers of dysfunctional adipose tissue, plasma levels of several cytokines including TNF-α, IL-6 and adiponectin are independent predictors of T2D." (PMID 33322261, 2020). "Pro-inflammatory adipokines (IL-6, TNF-α, MCP-1) and leptin, associated with the maintenance of the obese state, are elevated during the obese state whereas adiponectin, which plays an important role in insulin sensitivity, is decreased, connecting its role to insulin resistance and T2DM." (PMID 32903449, 2020). "It has been reported that the serum levels of IL-6 and hs-CRP (high-sensitivity C-reactive protein) in patients with GDM are significantly increased, but the mechanism is not fully understood, and the causal relationship with insulin resistance is still controversial." (PMID 32280713, 2020). "Moreover, TLR2 and TLR4 activity was markedly increased in association with elevated TNF-α, IL-6, and IFN-γ expressions, increased insulin resistance in response to inflammation; the changes were more prominent in diabetic patients with end-stage renal disease and renal failure." (PMID 33442388, 2020). "In addition, several reports have indicated that high circulating concentrations of inflammatory mediators (including CRP, IL-6, TNF-α, and MCP-1) originate from obese adipose tissue and that the levels of these mediators are associated with the degree of insulin resistance." (PMID 31192262, 2019). "In fact, the 4 h pretreatment of L6 rat myoblast cell line with alantolactone (at 0.5 μM), followed by 24 h exposure to IL-6, caused a decrease in the IL-6 induced insulin resistance and allowed the increase of glucose uptake levels to the levels of the control group (without exposure to IL-6)." (PMID 31064136, 2019). "Moreover, the skeletal muscle-derived IL-6 has been suggested to have beneficial effects, modulating glucose and fatty acid metabolism during exercise but also contributing to the development of insulin resistance when chronically elevated." (PMID 30863477, 2019). "Furthermore, the reduction in IL-6 was not related to changes in insulin resistance, suggesting reduction of ASP by atorvastatin as the underlying mechanism for reducing inflammatory markers." (PMID 31293514, 2019). "Moreover, lipolysis may be stimulated by IL-6, and insulin resistance in muscle may be induced by adipocyte-derived IL-6." (PMID 30717377, 2019). "Interestingly, our study also revealed a significant relationship between smoking status and intraocular levels of IL-6 in DR, and this association did not diminish after adjustment for insulin resistance." (PMID 31396410, 2019). "Thus, enhanced serum GLP-1 levels induced by inulin may be correlated with the reduction of IL-6 production and secretion and the suppression of hepatic gluconeogenesis, resulting in the moderation of insulin resistance in diabetic rats." (PMID 29507837, 2018). "Studies have suggested that IL-6 could be involved in insulin resistance and its complications." (PMID 29466985, 2018). "Therefore, TNF-α, IL-1β and IL-6 secretion under high fructose consumption may account for insulin resistance, chronic inflammation and endothelial dysfunction in local tissues and organs." (PMID 28353649, 2017). "In this study, we suggested that the prevalence of Gram-negative species in the gut and the increased plasma IL-6 in patients could be linked to low-grade inflammation and insulin resistance." (PMID 28966614, 2017). "Thus, inflamed adipose tissue could promote low-grade systemic inflammation by releasing proinflammatory cytokines and chemokines (IL-1ß, TNF-α, IL-6, leptin, CCL2, CCL3, and CXCL8) and causing insulin resistance and endothelial dysfunction." (PMID 28512338, 2017).
Insulin resistance (continued). "Although chronic elevation of IL-6 is typically regarded as detrimental to insulin resistance and cardiovascular health, acute oscillations in IL-6, as seen for example following exercise, may be important in maintaining insulin sensitivity in muscle post-exercise." (PMID 26514561, 2017). "IL-6 may be involved in the cause of insulin resistance since its blood concentration is high in obese individuals and in type 2 diabetic patients, and expression of the IL-6 gene is increased in the subcutaneous WAT of individuals with insulin resistance." (PMID 28168013, 2017). "Moreover, the secretion of various adipokines, such as tumor necrosis factor α (TNFα), interleukin-6 (IL-6), and adiponectin may play a role in the relation between insulin resistance and the development of HCC." (PMID 26913058, 2016). "Since insulin resistance and metabolic dysfunction are closely related to inflammatory status, we checked proinflammatory cytokine levels in plasma, and found plasma levels of IL-1β and IL-6 were reduced by LFE treatment (300 mg/kg) (by 98.2 ± 12.0% and 35.3 ± 8.96%, respectively)." (PMID 27176632, 2016). "As the potential effector molecules involved in insulin resistance, the levels of mTOR, phosphorylated mTOR and downstream phosphorylated S6K were increased in the TNF-α and IL-6-treated groups, suggesting that the mTOR/S6K pathway may be involved in insulin resistance under inflammatory stress." (PMID 26449763, 2015). "Indeed, ROS, IL-6 and TNFα were reported to impair the normal differentiation of preadipocytes and lipid accumulation contributing to inflammation-induced adipose tissue dysregulation and insulin resistance." (PMID 25685071, 2015). "Therefore, an IL‐6 paradox does exist, such that elevated IL‐6 can lead to the development of insulin resistance, and yet may also lead to increased insulin sensitivity." (PMID 24997069, 2014). "Since elevated inflammatory factors were closely associated with impaired glucose tolerance and insulin resistance, we assessed the expression of TNF-α and IL-6 to investigate whether changes in inflammatory status could link the maternal HFolS to insulin resistance." (PMID 24736781, 2014). "According to previous data, our results indicate that the induction of proinflammatory cytokines, IL-6 and TNF-α production, caused in PBMs stimulated by LPS, is similar to that observed in obese subject, where metabolic disorders, proinflammatory state and insulin resistance are often associated." (PMID 25368579, 2014). "These elevated IL-6 levels may have links with insulin resistance and hyperandrogenism." (PMID 25096410, 2014). "TNF-α and IL-6 are potent inhibitors of adiponectin expression and secretion in WAT biopsies and culture cells, suggesting that insulin resistance induction by TNF-α and IL-6 may also be caused by an inhibition of the autocrine-paracrine liberation of adiponectin." (PMID 24741627, 2014). "It is possible that during insulin resistance, increased IL-6 not only diminishes insulin sensitivity but by suppressing insulin signal transduction also interferes with anti-inflammatory effect of insulin, and might favour inflammation during insulin resistance." (PMID 23805905, 2013). "Amongst several mediators, tumor necrosis factor (TNF) and interleukin-6 (IL-6) were shown to promote both insulin resistance and cardiac hypertrophy, suggesting that inflammation in metabolic syndrome might be a central feature in atherogenesis as well as in cardiac hypertrophy." (PMID 23365487, 2013). "Long-term exposure to IL-6 may then, paradoxically, induce insulin resistance." (PMID 23737652, 2013).
Insulin resistance (continued). "MSG may cause obesity and nonfatty liver and increased mRNA level of IL-6, TNFα, resistin, and leptin in visceral fat tissue, which might all predispose insulin resistance in later life." (PMID 24455747, 2013). "Given that TNF-α and IL-6 as well as the NF-κB activation are crucial for the development of glucose intolerance and insulin resistance, our data support the notion that inhibition of inflammation-related NF-κB activation may be a promising strategy for the intervention of glucose intolerance." (PMID 23326455, 2013). "The administration of HCD in piglets has been associated with hepatic steatosis, insulin resistance, and hepatic inflammation, including increased myeloperoxidase activity and expression of proinflammatory cytokines and chemokines, particularly IL-2, CXCL2, TNFα, and IL-6." (PMID 23565157, 2013). "The anti-inflammatory properties of MTX may have helped to ameliorate the severity of diabetic pathology in our study, given the known involvement of inflammatory cytokines such as hsCRP, IL-6 in the development of insulin resistance, type 2 diabetes, and its long-term cardiovascular complications." (PMID 22778921, 2012). "During insulin resistance, increased IL-6 might not only diminish insulin sensitivity by suppressing insulin signal transduction but also interfere with anti-inflammatory effect of insulin, and might favour inflammation during insulin resistance." (PMID 22144985, 2011). "Interestingly, it also has been found that, both, IL-6 serum levels and insulin resistance increase with age, indicating that IL-6 might also be involved in the molecular regulation of aging." (PMID 21179199, 2010). "The causal role of IL6 in the development of insulin resistance and type 2 diabetes is not clear." (PMID 19243600, 2009). "Elevated insulin resistance, hs-CRP, and IL-6 among women with EIN/EC are consistent with prior work linking excess adiposity to chronic low-grade inflammation and altered endocrine signaling." (PMID 41595367, 2026). "Significant correlations between NOX2, HbA1c, glucose, IL-6, COX-2, and Caspase-3 confirm NOX2’s central role in T2D pathophysiology, as a mediator between inflammation and insulin resistance." (PMID 41607455, 2026). "A higher proportion of women with EIN/EC exhibited elevated insulin resistance, hs-CRP, IL-6/TNF-α, and MDA levels compared with the leiomyoma group." (PMID 41595367, 2026). "Pro-inflammatory cytokines, such as interleukin-6 (IL-6), tumor necrosis factor-alpha (TNF-α), and interleukin-1β (IL-1β), disrupt insulin signaling, impair β-cell function, and exacerbate insulin resistance." (PMID 41578487, 2026). "High VAT content promotes inflammation and tumor progression via cytokine secretion (leptin, resistin, IL-6, and TNF- α), angiogenesis, and insulin resistance." (PMID 40699302, 2026). "Pro‐inflammatory macrophages, characterized by elevated expression of CD11c+ and Nos2, secrete inflammatory cytokines such as TNF‐α, IL‐6, and IL‐1β, thereby inhibiting GLUT4 expression and worsening insulin resistance." (PMID 41509193, 2026). "The final model included 5 independent predictors: polycystic ovary syndrome (PCOS), homeostatic model assessment for insulin resistance (HOMA-IR), interleukin-6 (IL-6), high-density lipoprotein cholesterol (HDL-C), and serum uric acid." (PMID 42071836, 2026). "Circulating FGL2 positively correlated with glycemic indices, insulin resistance, lipid parameters, renal tubular injury markers (NGAL, KIM-1), inflammatory cytokines (TNF-α, IL-6), and fibrotic mediators (TGF-β1, CTGF)." (PMID 42161877, 2026). "Statins have also been associated with heightened systemic inflammation, characterized by elevated levels of pro-inflammatory markers such as interleukin-6 (IL-6) and tumor necrosis factor-alpha (TNF-α), which exacerbate insulin resistance." (PMID 39981479, 2025).